KCNQ2 (potassium voltage-gated channel subfamily Q member 2)
Diseases named in the same sentence as KCNQ2 in open-access papers (continued):
Sharing a sentence is not in itself a finding about the gene and the disease.
Encephalopathy (31 papers, 2014 to 2025). Encephalopathy is a term that means brain disease, damage, or malfunction. "Donepezil should be repurposed as a novel alternative treatment for GoF variants in KCNQ2/KCNQ3 encephalopathy." (PMID 39175503, 2024). "KCNQ2 R201H is a pathogenic Gain of Function variant that leads to a severe neonatal-onset encephalopathy with prominent startle-like myoclonus, infantile onset epilepsy, and a burst-suppression electroencephalography pattern." (PMID 37443005, 2023). "Since most patients with KCNQ2 encephalopathy carry a heterozygous mutation, we evaluated the ability of KCNQ openers in clinical trials (RTG, HN37, and XEN1101) to rescue the function of mutations in the heteromeric configuration." (PMID 36932231, 2023). "Similar to the results of our data, Millichap and colleagues report a similar clustering of case variant propensity solely in the pore region and CR2 for mutations of KCNQ2 associated with encephalopathy." (PMID 37897496, 2023). "The R198Q mutation in KCNQ2 channels causes infantile spasms with hypsarrhythmia and encephalopathy associated with severe developmental delay." (PMID 35642783, 2022). "The gene KCNQ2 was involved, the haploinsufficiency of which causes neonatal seizures and encephalopathy." (PMID 34616436, 2021). "In contrast, we showed that three pore domain mutations, a well-studied experimental mutation of the selectivity filter, G279S, and two of the most highly recurrent human KCNQ2 encephalopathy variants, T274M and A294V, strongly prevent AIS trafficking." (PMID 33041849, 2020). "Here, we analyze the functional consequences of A337T and A337G, two KCNQ2 encephalopathy variants, at a conserved residue in the CaM-binding Helix A." (PMID 33041849, 2020). "Individuals with pathogenic KCNQ2 encephalopathy variants have ended their diagnostic odyssey, have a poor long-term prognosis, and are appropriate candidates for novel therapeutic trials." (PMID 33041849, 2020). "Novel Kv7 openers merit further study as a candidate therapy for KCNQ2 encephalopathy due to loss-of-function variants, including those in the CT region that impair PIP2 modulation." (PMID 33041849, 2020). "Our findings highlight the importance of PIP2 interaction in causation and potential therapy for KCNQ2 encephalopathy." (PMID 33041849, 2020). "Variants in KCNQ2 can underlie a severe syndrome consisting of intractable neonatal onset seizures and profound global developmental delay called KCNQ2 encephalopathy." (PMID 33041849, 2020). "In affected families with BFNC, the individuals who later presented with delayed psychomotor development or mental retardation showed mutations located on the KCNQ2 gene suggesting an association between KCNQ2 mutations and encephalopathy." (PMID 25566516, 2014). "Our results, spanning structure to behavior, may be broadly applicable because the majority of KCNQ2 encephalopathy patients share variants near the selectivity filter." (PMID 38260608, 2024). "Although the most frequent KCNQ2 and KCNQ3 mutations are LoF, some KCNQ2 variants causing encephalopathy may present GoF characteristics, with increased channel activity, altered kinetics, and more severe clinical manifestation in affected patients." (PMID 38003469, 2023). "Together, these results suggest that disruption of Kcnq2 channel function in Phox2b-expressing neurons disrupts central chemoreception and may contribute to breathing problems associated with Kcnq2 encephalopathy." (PMID 38052789, 2023). "These rare variants, like nearly all of those found in KCNQ2 encephalopathy, cause clinical symptoms in heterozygous individuals, so the observed effects on CaM binding and protein expression may not contribute to clinical severity." (PMID 33041849, 2020).
Encephalopathy (continued). "Another example suggesting the potential predictive utility of data from variants expressed alone experiments is provided by a recent analysis of R144Q, R198Q, R201C, and R201H, KCNQ2 voltage-sensor domain variants associated with severe encephalopathy phenotypes." (PMID 33041849, 2020). "These burst suppression patterns with associated interictal multifocal spikes and polyspikes in association with the specific neonatal clinical epileptiform activity must be taken into account in the diagnostic work-up of neonatal encephalopathies, which also includes KCNQ2 testing." (PMID 25566516, 2014). "Moreover, most patients with KCNQ2 encephalopathy carry a heterozygous mutation; thus, the pharmacological responses in the condition when mutation co-expressed with KCNQ2 WT and KCNQ3 (1:1:2 ratio) may better represent the therapy response." (PMID 36932231, 2023). "However, as already discussed, the majority of patients will present with EOEE, often characterized by burst-suppression or a multifocal pattern and tonic/myoclonic seizures with limited specificity, as only KCNQ2 encephalopathy has been robustly associated with a typical seizure type." (PMID 33919646, 2021). "In the present study, we evaluated the therapeutic potential of donepezil, a reversible acetylcholinesterase inhibitor approved by the FDA, in four children affected by GoF variants of KCNQ2 and KCNQ3 encephalopathy." (PMID 39175503, 2024). "KCNQ2 and KCNQ3 variants can also lead to severe refractory epilepsy accompanied by encephalopathy and cognitive decline." (PMID 38003469, 2023). "According to the prognosis, we found that there were few patients with KCNQ2-related disorder whose outcome was between benign and encephalopathy." (PMID 34711204, 2021). "Although ezogabine has also shown some benefits in seizure control in several KCNQ2 encephalopathy infants, including an individual heterozygous for A337T, side effects have limited its use." (PMID 33041849, 2020). "Understanding these mechanisms can create opportunities for new targeted therapies for KCNQ2-encephalopathy." (PMID 33192566, 2020). "This is supported in KCNQ2 encephalopathy observed in one study with A294V29 and in the present study." (PMID 32770121, 2020). "Our patients with KCNQ2-p.E515D also differ with respect to typical EEG and seizure semiology patterns observed in KCNQ2 encephalopathy." (PMID 28686619, 2017). "Most of the reported KCNQ2 encephalopathies were diagnosed as Ohtahara syndrome showed a burst suppression EEG pattern and infrequently involuted to West syndrome with poor developmental outcome." (PMID 25566516, 2014). "Although it may offer targeted therapy for KCNQ2 encephalopathy, its application is limited due to its side effects, such as urinary retention and skin and retinal pigmentation." (PMID 40342533, 2025). "Additionally, sodium channels and KCNQ potassium channels can co-localize and are positioned in proximity within the neuronal membrane, with KCNQ2 encephalopathy representing another highly treatment-resistant epilepsy syndrome." (PMID 36902275, 2023). "The recent description of individuals with severe developmental delay with or without seizures due to pathogenic variants in KCNQ2 (KCNQ2-encephalopathy) reveals that Kv7.2 channels also have an important role in neurodevelopment." (PMID 33192566, 2020). "To begin to assess whether such “second generation” openers merit exploration as candidate therapeutic agents for KCNQ2 encephalopathy, we studied the effects of SF0034 on channels including the A337T pathogenic variant." (PMID 33041849, 2020). "And when we talk about KCNQ2 encephalopathy, are we referring to the Othahara or ESES syndrome?" (PMID 31907053, 2020). "However, several patients with a severe encephalopathy phenotype of KCNQ2-related neonatal seizures have also been reported." (PMID 25566516, 2014).
Encephalopathy (continued). "We found that both variants cause loss of current amplitude sufficient to be considered as dominant-negative, supporting the clinical diagnoses of KCNQ2 encephalopathy." (PMID 33041849, 2020).
developmental and epileptic encephalopathy (26 papers, 2019 to 2026). An epilepsy associated with developmental impairment that may be due to either the underlying etiology or the superimposed epileptic activity, or both. "Initially linked to self-limited neonatal epilepsy (SeLNE), de novo missense KCNQ2 mutations have also been associated with a more severe phenotype referred to as developmental and epileptic encephalopathy (KCNQ2-DEE)." (PMID 38474157, 2024). "Loss-of-function mutations in the KCNQ2 gene that encodes Kv7.2 cause KCNQ2 developmental epileptic encephalopathy (KCNQ2-DEE), a severe disorder that causes seizures and often profound developmental delay." (PMID 39390220, 2024). "Loss- and gain-of-function variants in the gene encoding KCNQ2 channels are a common cause of developmental and epileptic encephalopathy, a condition characterized by seizures, developmental delays, breathing problems, and early mortality." (PMID 38052789, 2023). "KCNQ2 mutations are associated with developmental and epileptic encephalopathy, benign neonatal seizures, and myokymia." (PMID 36011376, 2022). "KCNQ2-linked pathogenic variants include a range of overlapping neonatal epileptic phenotypes ranging from mild self-limited familial neonatal epilepsy to severe neonatal-onset developmental and epileptic encephalopathy." (PMID 39175503, 2024). "Mutations in the KCNQ2 gene encoding KV7.2 subunit that mediates neuronal M-current cause a severe form of developmental and epileptic encephalopathy (DEE)." (PMID 36932231, 2023). "In case 5 with KCNQ2-related Developmental and epileptic encephalopathy 7 (MIM#121200), vigabatrin was initiated based on literature-reported efficacy seven days prior to standard genomic care results, but due to a lack of effect, treatment was discontinued." (PMID 41116046, 2026). "For instance, XEN496 which is currently in a phase III trial, targets the potassium voltage-gated channel subfamily Q member 2 developmental and epileptic encephalopathy (KCNQ2-DEE), a specific epilepsy syndrome." (PMID 39865817, 2025). "This infant had voltage-gated potassium channel KCNQ2-Developmental and epileptic encephalopathy 7 (MIM:613700, PRR 14), a probable genetic etiology." (PMID 41358299, 2025). "Kcnq2 disfunction can cause developmental and epileptic encephalopathy (DEE)." (PMID 38052789, 2023). "Pathogenic variants in KCNQ2 have been linked to a range of neonatal epileptic disorders from self-limited neonatal epilepsy (SeLNE) to more severe neonatal-onset developmental and epileptic encephalopathy (DEE)." (PMID 37497102, 2023). "At the severe end of the KCNQ2 spectrum is an early-onset developmental and epileptic encephalopathy (DEE) characterized by recurrent seizures starting in the neonatal period and neurodevelopmental disability." (PMID 33013448, 2020). "Mutations in KCNQ2 are frequently associated with neonatal epilepsy, presenting in two main forms: self-limited familial neonatal epilepsy (SLFNE) and neonatal-onset developmental and epileptic encephalopathy (DEE)." (PMID 39971736, 2025). "Pathogenic variants in KCNQ2 encoding for Kv7.2 potassium channel subunits have been found in patients affected by widely diverging epileptic phenotypes, ranging from Self-Limiting Familial Neonatal Epilepsy (SLFNE) to severe Developmental and Epileptic Encephalopathy (DEE)." (PMID 35770094, 2022).
Benign familial neonatal seizures (23 papers, 2013 to 2026). Benign familial neonatal seizures (BFNS) is a rare epilepsy of the newborn characterized by partial or generalized seizures, which occur during wakefulness and/or sleep. "Truncating KCNQ2 pathogenic variants frequently cause benign familial neonatal seizures, whereas missense pathogenic variants cause severe neonatal encephalopathy." (PMID 39104744, 2024). "KCNQ2 was first discovered over 20 years ago as a gene likely to cause benign familial neonatal seizures, a form of a self-limiting pediatric epilepsy disorder." (PMID 33863780, 2021). "Among neonatal epileptic syndromes, benign familial neonatal seizures (BFNS) are often due to autosomal-dominant mutations of the KCNQ2 gene." (PMID 31552204, 2019). "A KCNQ2 variant previously associated with benign neonatal seizures is present in 3 of 12 individuals in the severe category." (PMID 28686619, 2017). "Spontaneous mutations one of the KCNQ2 genes cause disorders of neural excitability such as Benign Familial Neonatal Seizures." (PMID 23977150, 2013). "The human KCNQ2 gene is susceptible to a variety of mutations, many of which give rise to a form of infantile epilepsy (benign familial neonatal seizures, BFNS), and sometimes to forms of peripheral nerve hyperexcitability such as myokymia." (PMID 23977150, 2013). "While KCNQ2 mutations are known to cause a spectrum of diseases, from benign familial neonatal seizures (BFNS1) to drug-resistant DEE7, the clinical outcomes specifically associated with large deletions-a rare mechanism causing haploinsufficiency-are not well defined." (PMID 42221008, 2026). "Indeed, the same SNP was reported in a patient with benign familial neonatal seizures who, in addition, carried a de novo mutation in KCNQ2 that changed channel gating." (PMID 23596459, 2013). "However, several mutations in KCNQ1 leading to a “long QT syndrome” of cardiac arrhythmias (Y111C, L114P, and P117L) or Benign Familial Neonatal Seizures (R353G and L339R) mutations in KCNQ2 reduced channel expression via effects on trafficking of the channels." (PMID 26692086, 2015). "The members of the KCNQ family, especially KCNQ2 and KCNQ3, encode voltage-gated potassium channels (VGKC), which are associated with epilepsy, such as benign familial neonatal seizures (BFNS)." (PMID 36835631, 2023). "For e.g. variations in KCNQ2 and KCNQ3 having 85% penetrance are identified as causal factor of benign familial neonatal seizures." (PMID 33096746, 2020). "Benign familial neonatal seizures (BFNS) as another early-onset epilepsy have been revealed to be associated with loss-of-function mutations of voltage-gated potassium channel genes, including KCNQ2 (potassium voltage-gated channel subfamily Q member 2) and KCNQ3." (PMID 36835631, 2023). "Thus, in retrospect it is not surprising that KCNQ2 pathogenic variants lead to range of pediatric epilepsy disorders from benign familial neonatal seizures to DEEs." (PMID 33863780, 2021).
Seizure (18 papers, 2014 to 2025). A seizure is an intermittent abnormality of nervous system physiology characterized by a transient occurrence of signs and/or symptoms due to abnormal excessive or synchronous neuronal activity in the brain. "Seizures caused by hypocalcemia or KCNQ2 mutations occur most frequently in the first 2 weeks after birth." (PMID 34414144, 2021). "OXC was considered more efficacious for KCNQ2‐associated seizures in several studies, which is consistent with our findings." (PMID 31199083, 2019). "In a prospective cohort of neonates with seizures enrolled in the multicentre US Neonatal Seizure Registry, neonatal EE was found in 13% of patients (79/611), and 83% had a genetic etiology, with KCNQ2 variants the most common." (PMID 33603712, 2021). "KCNQ2 has been reported in three Saudi patients with epileptic seizures starting in the first four months of life." (PMID 37628333, 2023). "This is due only in part to the early start of seizures in DEE but also to the infantile manifestation of focal seizures in benign familial infantile epilepsies, which may be caused by variants in the PRRT2, KCNQ2, SCN2A, like in our cohort." (PMID 38328757, 2023). "The KCNQ2 variant identified in individual ID#6 and the non-affected mother belongs to a large family of genes encoding potassium channels associated with benign neonatal seizures, but the role of this variant in the BrS phenotype of this family remains unclear." (PMID 29261713, 2017). "Seizures are highly penetrant in human SLFNE pedigrees, but no Kcnq2 SLFNE mouse model known to date shows spontaneous seizures." (PMID 38260608, 2024).
channelopathies (14 papers, 2016 to 2025). "This study provides insight into KCNQ2 channel function, which will aid in uncovering the mechanisms underlying channelopathies." (PMID 35642783, 2022). "In channelopathies, seizures usually present as tonic (focal or general), such as those exhibited in KCNQ2, SCN2A and SCN8A genetic mutations." (PMID 34833120, 2021). "The most frequent variants that cause DDE, associated with channelopathies, disrupt the function of the genes that encode voltage-dependent sodium and potassium channels, such as, for example, SCN2A and KCNQ2." (PMID 39858526, 2025). "In the case of six patients with variants in other channelopathy-related genes (SCN1A, SCN2A, SCN8A, and KCNQ2), the previous literature guided the choice of anti-seizure medication." (PMID 37645600, 2023). "Since KCNQ2 channels play a pivotal role in controlling neuronal excitability, these results provide critical clues to aid in our understanding of the impact of channelopathies on neuronal function." (PMID 35642783, 2022). "Previous studies have shown that the biophysical properties of channelopathy-causing variants, such as SCN1A, KCNA2, KCNQ2, and GluN2B may correlate with phenotypes." (PMID 35845605, 2022). "Other overlapping events of channelopathies and neurometabolic disorders include consciousness change due to seizure or antiepileptic intravenous medications, SB patterns in some channels and KCNQ2 groups and, in some metabolic disorders, refractory seizure after antiepileptic medications." (PMID 34833120, 2021). "Among molecularly diagnosed cases SCN1A, SCN2A, KCNQ2, SCN8A, and ATP1A2 were identified as channelopathy-related genes, representing 7 patients." (PMID 40083435, 2025). "Low-voltage fast activity followed by recruiting spikes or theta rhythms arising mainly from the central regions of either hemisphere followed by focal spike-wave complexes and prolonged focal or diffuse postictal attenuation could be seen in channelopathies, such as KCNQ2 and SCN2A channelopathy." (PMID 34833120, 2021).